CERS4 (ceramide synthase 4)
Diseases named in the same sentence as CERS4 in open-access papers (continued):
Sharing a sentence is not in itself a finding about the gene and the disease.
liver steatosis (1 paper, 2024). "For liver steatosis, the CERS4 rs17160348 TT genotype, PLA2R1 rs3749117 CC genotype, and PLA2R1 rs3749117 CC genotype had significantly higher steatosis proportions than the other 2 genotypes, respectively, while PON1 rs854560 TT genotype had the lower steatosis proportion than the wild genotype." (PMID 38836837, 2024).
pancolitis (1 paper, 2022). Ulcerative colitis that involves the entire colon. "CerS4 LCK/Cre mice developed significantly more tumors per mouse in comparison with CerS4 WT, CerS4 KO, and CerS4 Vil/Cre mice and suffered from pancolitis, indicating a crucial role of CerS4 in T-cells for resolution of inflammation." (PMID 35163788, 2022). "CerS4 KO and CerS4 LCK/Cre mice, which had the highest scores, suffered most from pancolitis." (PMID 35163788, 2022). "In 66% of all investigated tissue slices of CerS4 LCK/Cre mice, the inflammation extended from the distal to the proximal part of the colon (pan), while in CerS4 KO mice, about 50% of all slices exhibited pancolitis." (PMID 35163788, 2022).
steatosis (1 paper, 2024). Increased lipid within the cytoplasm of cells. "Mutations in PLA2R1 rs35771982 and CERS4 rs17160348 are associated with susceptibility to MASLD in nonobese individuals, while PLA2R1 rs35771982 mutation is a risk factor for moderate-to-severe steatosis and steatohepatitis in nonobese patients." (PMID 38836837, 2024).
virus infection (1 paper, 2025). "Thus, it would be interesting to determine if CerS4 has similar or different roles during other virus infections for a deeper understanding of ceramide/CerS4-virus interactions." (PMID 41217173, 2025). "The results imply that the inhibition of viral replication by CerS4 did not occur at very early steps of viral infection such as viral entry." (PMID 41217173, 2025). "The function of CerS4 in viral infection has not been explored." (PMID 41217173, 2025). "As the in vitro overexpression of CerS4, but not CerS1, inhibited influenza virus replication, it is possible that specific ceramide subspecies synthesized in cells may be critical for the host defense against virus infection." (PMID 41217173, 2025).
tumor (10 papers, 2015 to 2026). "In conclusion, the deficiency of CerS4 in T-cells led to an enduring active status of these cells and prevents the resolution of inflammation, leading to a higher tumor burden in the CAC mouse model." (PMID 35163788, 2022). "Further cell-type-specific depletion of CerS4 indicated that an intestinal epithelial-specific CerS4 depletion in mice has a protective effect against the AOM/DSS-induced colon carcinogenesis, suggesting that loss of CerS4 in colon epithelial cells protects cells for tumour-promoting signals." (PMID 38635059, 2024). "It has been shown that CerS4 is downregulated in K-Ras mutant tumours and by depletion of Myc, which is a direct transcriptional regulator of CerS4." (PMID 38635059, 2024). "These analyses revealed significantly higher CERS4 mRNA expression levels in tumor tissues than in normal tissues in two cohorts (TCGA-BRCA, P < 0.0001; GSE115577, P < 0.0001)." (PMID 37885013, 2023). "Conversely elevated de-novo C18-ceramide, synthesised by CerS4 in the liver, was also found to function as a powerful pro-apoptotic activator in tumour cells." (PMID 26863224, 2016). "Notably, B4GALNT1 upregulation and CERS4 downregulation correlated with advanced tumor stage and metastasis." (PMID 41666167, 2026). "However, the previous study examining CerS4 overexpression used transient plasmid transfection, whereas the present study investigated the effects of long-term CerS4 overexpression on tumor progression and chemoresistance in MCF-7 cells." (PMID 37885013, 2023). "Downregulation of CerS4 in early tumor stages might have opposite effects." (PMID 35163788, 2022). "The higher tumor incidence in CerS4 LCK/Cre mice and the toxic effect of AOM/DSS in CerS4 KO mice exhibited the importance of CerS4 in other tissues and revealed the complexity of general targeting CerS4." (PMID 35163788, 2022). "Depletion of CerS4 in T-cells inhibited resolution of inflammation after AOM/DSS treatment and enhanced tumor formation." (PMID 35163788, 2022). "Although the tumor number was higher in AOM/DSS-treated CerS4 LCK/Cre mice, the tumor volume was lower than in WT mice." (PMID 35163788, 2022). "CERS4 (ceramide synthase 4) generates ceramide, which binds to Smad7 and limits the aggregation of TGF-β receptor in the primary cilia, thereby blocking tumor cell migration." (PMID 33996533, 2021). "Accordingly, in in vitro experiments, downregulation of CerS4 in aggressively growing tumour cells such as SW620 and HCT-116 has been shown to have pro-proliferative effects in a 3D organoid model in vitro and in a xenograft tumour model in nude mice." (PMID 38635059, 2024). "The high abundance of M2-like macrophages in the colon tissue of AOM/DSS-treated CerS4 LCK/Cre mice might contribute to the higher tumor incidence in these mice, because M2 cells promote tissue remodeling, angiogenesis, and tumor progression." (PMID 35163788, 2022). "Therefore, low level of CerS4 and C18-Cer counteracts the inhibitory effect of HDAC1/SP3 on the hTERT promoter, increases hTERT transcription and has pro-proliferative effects at least in aggressively growing tumours." (PMID 38635059, 2024). "In contrast, the gene expression of CERS4 and CERS5, but not ASAH1, was significantly increased in HCC tumors than that in non-tumor adjacent tissues." (PMID 33803928, 2021). "Data mining of our previous human HCC transcriptome dataset showed that the gene expression of CERS2, CERS4, CERS5, and CERS6 was significantly increased in HCC tumors compared with that in non-tumor adjacent tissues, while no obvious difference was observed in ASAH1 gene expression." (PMID 33803928, 2021).
cancer (9 papers, 2015 to 2025). A tumor composed of atypical neoplastic, often pleomorphic cells that invade other tissues. "CerS4 was found to be associated with many cancer-related signaling pathways, chemoresistance, and EMT." (PMID 37885013, 2023). "Persistent CerS4 overexpression in MCF-7 cells activated multiple cancer-associated pathways, including pathways involving sterol regulatory element–binding protein, nuclear factor kappa B (NF-κB), Akt/mammalian target of rapamycin (mTOR), and β-catenin." (PMID 37885013, 2023). "Finally, CERS4 knockdown in doxorubicin-resistant MCF-7/ADR cells resulted in reduced activation of cancer-associated pathways (NF-κB, Akt/mTOR, β-catenin, and EMT) and diminished chemoresistance, accompanied by ABCB1 and ABCC1 downregulation." (PMID 37885013, 2023). "CerS4, which catabolizes the synthesis of C18–C20 ceramides, regulates cancer cell migration and invasion." (PMID 35565311, 2022). "Knockdown of CerS4 increases migration in A549 cells, and the restoration of CerS4 generates C18–C20 ceramides to inhibit cancer cell migration and invasion." (PMID 35565311, 2022). "Together, all of the alterations induced by stable CerS4 overexpression may contribute to the development of chemoresistance and cancer progression." (PMID 37885013, 2023). "This implies that CERS4 expression was reduced in the KRAS mutation group, potentially resulting in a diminished proapoptotic effect, may be why low-CERS4 cancers had more venous invasion." (PMID 37758931, 2023). "CerS4 overexpression in MCF-7 cells also increased cell cycle-related and cancer-related gene expression, suggesting that CerS4 overexpression could accelerate cell division and proliferation." (PMID 37885013, 2023). "However, our CerS4 VilCre mouse data showed the opposite effect, which might be related to the cancer model used herein." (PMID 35163788, 2022). "In prior cancer research, CerS1, but not CerS4, increased cellular sensitivity to cisplatin, a chemotherapeutic drug, with enhanced cell death." (PMID 41217173, 2025). "Chronic CerS4 overexpression in MCF-7 cells also altered several critical signaling pathways, including Akt/mTOR, NF-κB, and β-catenin, which play essential roles in cancer development and progression." (PMID 37885013, 2023). "Additionally, interesting research has been published on CerS4 generated C18–C20-ceramide induction of TGF-β receptor I/II to primary cilia, which increased cancer cell migration and metastasis." (PMID 34069611, 2021). "Interestingly, CerS6 itself, but not CerS4, induced strong antiproliferative effect in several cancer cell lines if elevated by transient transfection." (PMID 26783755, 2016). "Furthermore, while the elevation of CerS6 through a transient transfection induced strong antiproliferative effect in several cancer cell lines, the expression of CerS4 in our experiments had no noticeable effect on proliferation of A549 or HCT116 cells." (PMID 26783755, 2016).
infection (2 papers, 2022 to 2025). The state of being infected such as from the introduction of a foreign agent such as serum, vaccine, antigenic substance or organism. "To further evaluate CerS4 degradation during infection, we used inhibitors that block proteasomal (MG132) or lysosomal (NH4Cl and Bafilomycin A1) protein degradation pathways." (PMID 41217173, 2025). "The inhibition of viral protein expression by CerS4 was observed upon influenza A/WSN/33 (H1N1) (IAV WSN) or pH1N1 at multiple time points after infection." (PMID 41217173, 2025). "Following the downregulation of CerS4 with si-CerS4, an increase in viral protein expression levels was observed at both 12 and 24 hours post-infection (hpi) with IAV pH1N1 compared to scrambled siRNA control (SCR)." (PMID 41217173, 2025). "Taken together, these data indicate that overexpressed CerS4 displays antiviral function and impairs the productive infection of influenza viruses." (PMID 41217173, 2025). "A similar pattern of viral RNA regulation was detected when CerS4 was transiently overexpressed in A549 cells followed by pH1N1 infection." (PMID 41217173, 2025). "However, influenza virus may strive to counteract the antiviral activity of CerS4 as infection triggers degradation of CerS4, which in turn could promote a cellular environment advantageous for the replication of influenza viruses." (PMID 41217173, 2025). "The inhibition of viral protein expression by CerS4 was also observed when cells were infected with pH1N1 at an MOI of 3.0 for 8 h, representing a single-cycle infection condition." (PMID 41217173, 2025). "The function of CerS4 during infection with other viruses has not yet been reported to the best of our knowledge." (PMID 41217173, 2025). "However, the levels of mRNA encoding CerS4 did not significantly decrease upon IAV infection, suggesting that CerS4 regulation takes place at the post-transcriptional level during infection." (PMID 41217173, 2025). "IL-10 and IFNγ CD4+ cells are important for a chronic, nonresolving infection status, and together with the elevated TNFα and IL-6 expression, these data fit well with the enhanced and prolonged inflammation in the colons of AOM/DSS-treated CerS4 LCK/Cre mice." (PMID 35163788, 2022).
immune diseases (1 paper, 2024). "In addition, genes related to immune diseases (e.g., BID, SMARCD3, ATP6V1E1, NFKB2), energy metabolism (e.g., HAO1, NDUFA7, CERS4, MTHFD1), and other factors were also screened." (PMID 38750582, 2024).
CERS4 also shares sentences with these, for which no sentence is quoted: type 2 diabetes (2 papers); adrenomyeloneuropathy (1); alopecia (1); Anxiety (1); asthma (1); Breast Invasive Carcinoma (1); cardiovascular diseases (1); cervical squamous cell carcinoma (1); chronic kidney disease (1); dyslipidemia (1); esophageal carcinoma (1); gestational diabetes mellitus (1); head and neck cancer (1); inflammatory bowel disease (1); melanoma (1); ovarian carcinoma (1); pancreatic adenocarcinoma (1); renal cell carcinoma (1); retinal degeneration (1); thyroid cancer (1).